ST8SIA5 (ST8 alpha-N-acetyl-neuraminide alpha-2,8-sialyltransferase 5)
Description:
Involved in the synthesis of gangliosides GD1c, GT1a, GQ1b, GP1c and GT3 from GD1a, GT1b, GM1b and GD3 respectively.
Synonyms: SIAT8-E; ST8SiaV; SIAT8E
Tractability: Antibody: UniProt predicts a signal peptide or a membrane-spanning region; the Human Protein Atlas places it where antibodies can reach. PROTAC: ubiquitination databases record sites on it.
Gene: Protein-coding gene on chromosome 18 (46,667,821 to 46,759,257, reverse strand). Ensembl gene ENSG00000101638.
Subcellular location: Golgi apparatus membrane
Subcellular location (Human Protein Atlas): Midbody; Plasma membrane
Pathways (Reactome):
Metabolism: Glycosphingolipid biosynthesis
Metabolism of proteins: Sialic acid metabolism
Gene Ontology:
Molecular function: protein binding; alpha-N-acetylneuraminate alpha-2,8-sialyltransferase activity; sialyltransferase activity
Biological process: carbohydrate metabolic process; glycosphingolipid biosynthetic process; N-glycan processing; oligosaccharide metabolic process; glycoprotein biosynthetic process
Cellular component: Golgi membrane
Genetic constraint (gnomAD): Loss-of-function variants: 24 observed, 40.87 expected, observed/expected ratio (o/e) 0.59, 90% interval 0.42 to 0.83. The upper end of that interval is the gene's LOEUF score, 0.83, which puts it in group 3 of 6, group 1 being the genes least tolerant of losing a copy. Missense variants: 465 observed, 521.63 expected, observed/expected ratio (o/e) 0.89, 90% interval 0.82 to 0.96. Synonymous variants: 198 observed, 212.61 expected, observed/expected ratio (o/e) 0.93, 90% interval 0.83 to 1.05.
Homologues: Orthologues: chimpanzee ST8SIA5 (99% identical), macaque ST8SIA5 (99% identical), dog ST8SIA5 (99% identical), guinea pig ST8SIA5 (94% identical), pig ST8SIA5 (91% identical), mouse St8sia5 (85% identical), rat St8sia5 (85% identical), tropical clawed frog st8sia5 (83% identical), zebrafish st8sia5 (73% identical). Paralogues in human: ST8SIA6 (36% identical), ST8SIA1 (35% identical), ST8SIA4 (28% identical), ST8SIA2 (26% identical), ST8SIA3 (26% identical).
Diseases named in the same sentence as ST8SIA5 in open-access papers:
ST8SIA5 is named in the same sentence as 5 diseases in open-access papers, as found by Europe PMC text mining. Sharing a sentence is not in itself a finding about the gene and the disease. The quoted sentences say what the papers report.
breast carcinoma (1 paper, 2016). "In comparison with MCF-10A cells, the aggressive breast cancer cell line MDA-MB-231 showed an increased number of differentially expressed genes including ST6GALNAC5 (7.33-folds), ST8SIA4 (14.81-folds) and ST8SIA5 (3.11-folds)." (PMID 28032858, 2016).
colon cancer (1 paper, 2021). "Decreased expression of ST8SIA5 from TCGA dataset was linked to a poor survival in patients suffering from colon cancer, and decreased ST8SIA5 transcript was also observed in a murine model of colitis-associated cancer." (PMID 34975914, 2021).
tumor (3 papers, 2023 to 2025). "ST8SIA5 encodes a sialyltransferase that modifies glycan structures on the tumor surface, and this glycosylation remodeling may shield UCEC cells from immune surveillance, limiting ICD-mediated immune activation." (PMID 40777132, 2025). "The Wilcoxon Rank Sum test revealed that ALG1L2, B3GNT3, and B3GNT8 were expressed at higher levels in tumor tissues, while HS6ST3 and ST8SIA5 were expressed at lower levels in tumor tissues (all P < 0.01)." (PMID 38097951, 2023). "FUT1, FUT2, B3GNT2, GCNT2, and ST8SIA5 are involved in the blood group biosynthesis, a synthesis of blood group antigens process, which are glycan structures on cell surfaces that can influence tumour cell interactions with the TME, including immune system components." (PMID 39457550, 2024).
cancer (2 papers, 2018 to 2021). A tumor composed of atypical neoplastic, often pleomorphic cells that invade other tissues. "In the CCLE database, expression of JUP, ITGB4, ST8SIA5, ST8SIA1, ST3GAL2, ST3GAL5 and B4GALNT1 in pan-cancer were explored." (PMID 34402716, 2021).
infection (1 paper, 2023). The state of being infected such as from the introduction of a foreign agent such as serum, vaccine, antigenic substance or organism. "In addition, infection with both strains modulated the expression of ST3Gal5 and ST8Sia5." (PMID 37515094, 2023).